HK2 (hexokinase 2)
Diseases named in the same sentence as HK2 in open-access papers (continued):
Sharing a sentence is not in itself a finding about the gene and the disease.
liver cancer (continued). "The data from this study collectively suggested that the miR-885-5p/HK2 axis has additional potential to be explored as a therapeutic target and prognostic biomarker of liver cancer." (PMID 34680611, 2021). "In a recent study on liver cancer, it was discovered that miR-885-5p directly targets Hexokinase 2 (HK2) to regulate the Warburg effect." (PMID 34680611, 2021). "Mammalian target of rapamycin–signal transducer and activator of transcription 3 (mTOR–STAT3) can inhibit liver cancer cell glycolysis by inhibiting hexokinase 2 (HK2)." (PMID 33607990, 2021). "Overall, our results showed that CK reduced the expression of PDK1 and HK2, inhibited extracellular acidification, and inhibited the uptake of glucose by liver cancer cells." (PMID 33363466, 2020). "At the protein level, all established human liver cancer cell lines we examined express HK2 and lack HK4." (PMID 29988332, 2018). "A high-throughput screen was performed to search for synthetically lethal compounds in combination with HK2 inhibition in HK1−HK2+ liver cancer cells, and a combination therapy for liver cancers with this phenotype was developed." (PMID 29988332, 2018). "Perhexiline, a fatty acid oxidation inhibitor, further sensitizes HK1−HK2+ liver cancer cells to the complex I/HK2-targeted therapeutic combination." (PMID 29988332, 2018). "To confirm and extend these observations, we evaluated the expression of HK1 and HK2 in human liver samples and in a collection of liver cancer cell lines." (PMID 29988332, 2018). "Using an HK1−HK2+ subpopulation of liver cancers as an example, we developed a synergistic combination of HK2 inhibition and partial inhibition of mitochondrial complex I and fatty acid oxidation to achieve synthetic lethality of these HK1−HK2+ tumors." (PMID 29988332, 2018). "Studies have found that morusin could effectively reduce the expression of HK2 in liver cancer cells, inhibit cell glycolysis, thereby impeding cell proliferation and reducing cellular activity." (PMID 39991762, 2025). "Another study of Affiliated Hospital of Nantong University indicated that knocking down USP14 significantly inhibits the proliferation, invasion, and metastasis of liver cancer cells, promotes apoptosis, and simultaneously suppresses the expression of hexokinase 2 (HK2)." (PMID 40607251, 2025). "HK2 has been shown to interact with the mitochondria and contribute to liver cancer progression." (PMID 36335239, 2022). "Hexokinase 2 (HK2) is a novel stimulus for liver cancer stem cells." (PMID 35603967, 2022). "HK2 further facilitates the maintenance and self‐renewal of liver cancer stem cells." (PMID 35603967, 2022). "Autophagy regulates glycolytic metabolism by hexokinase 2 degradation in liver cancer." (PMID 34120890, 2021). "In addition, the involvement of HK2 has also been documented in esophageal squamous cancer, pancreatic cancer and liver cancer 21-23." (PMID 34345220, 2021). "While HK2 knockdown in HK1−HK2+ liver cancer cells substantially reduced cell proliferation, the majority of the cells remained alive; after removing DOX from cultured Hep3B/shHK2DOX cells, the DOX-treated HK1−HK2+ cells were able to recover from HK2-inhibited cytostasis and resumed proliferation." (PMID 29988332, 2018). "Furthermore, we investigated whether sh-USP14 inhibits the AKT and SQSTM1 signaling pathways in liver cancer cells by regulating HK2." (PMID 38383348, 2024). "Therefore, based on the key role of HK in HCC, HK2 may become a target for the development of new therapies for liver cancer." (PMID 37663261, 2023). "Knockdown of BFSP1 reduced the contents of pyruvate and lactic acid, the activities of HK2, PFK1, and PKM2, as well as the glucose uptake in liver cancer cells, whereas overexpression of BFSP1 plays the opposite role." (PMID 40097750, 2025).
liver cancer (continued). "USP14 regulates the autophagy function of liver cancer cells by regulating the interaction between SQSTM1/P62 and HK2." (PMID 38383348, 2024). "To investigate the role of USP14 in regulating liver cancer, we conducted an experiment focusing on the interaction between USP14 and HK2." (PMID 38383348, 2024). "In liver cancer, TRAF6-mediated K63 ubiquitination of HK2, leading to HK2 degradation through autophagy, negatively regulates glycolysis." (PMID 37190313, 2023). "Quercetin has been found to reduce HK2 levels and inhibit the AKT/mTOR pathway in liver cancer cells in vivo and in vitro." (PMID 37663261, 2023). "The results indicated that glycolysis markers, including PKM2, STMN1, MCT4, GLUT1, HK-2, CA9, and GLUT2, can serve as potential prognostic biomarkers and therapeutic targets for liver cancer." (PMID 38114977, 2023). "By increasing miR-199a, Dau directly downregulated HK2 and PKM2, inhibited glycolysis and increased OXPHOS, inhibited liver cancer cell proliferation, and sensitized sorafenib therapy." (PMID 37663261, 2023). "Subgroup analysis based on specific glycolysis markers revealed that higher expression of PKM2 (P < 0.001), STMN1 (P = 0.002), MCT4 (P < 0.001), GLUT1 (P = 0.025), HK-2 (P < 0.001), and CA9 (P < 0.001) was significantly correlated with poor OS in liver cancer." (PMID 38114977, 2023). "Wogonin has been demonstrated to decrease the expression of HK2, LDHA, and GLUT1, hence reducing glycolysis and cell proliferation in ovarian and liver cancer cells." (PMID 36339566, 2022). "The findings illuminated that compared with the blank control (vector), overexpression of lncRNA ZNF674-AS1 inhibited the expression of key proteins HK2, PFKL, PKM2, and GLUT1 in the glycolysis process of liver cancer SMMC-7721 and HepG2 cells." (PMID 35874626, 2022). "In this study, researchers also found that blocking HK2 or ACSL4 effectively inhibited cancer progression, which provides a promising therapeutic strategy for the treatment of liver cancer." (PMID 36497375, 2022). "Genistein sensitized liver cancer cells to apoptosis, directly regulating HIF1α, inactivating GLUT1 and Hexokinase 2 (HK2) to suppress aerobic glycolysis." (PMID 33918290, 2021). "In liver cancer cell lines such as Hep3B, HepG2, JHH5, JHH7, and Huh7, the expression of HK2 has been observed, while in other cancers such as lung, breast, colon, and also in HLF and HH6, liver cancer cell lines are expressed as both HK2 and HK1." (PMID 33809480, 2021). "Western blotting results showed that Glut1, HK2, LDHA, and PDK1 expression increased and the CCK8 assay showed that knocking out Bclaf1 promoted the reduction by CK of hypoxic liver cancer cell viability." (PMID 33363466, 2020). "Synthetic lethality was achieved in HK1−HK2+ liver cancer cells, by the combination of DPI, a mitochondrial complex I inhibitor, and HK2 inhibition, in HK1−HK2+ liver cancer cells." (PMID 29988332, 2018). "To examine tumor cell growth inhibition in response to HK2 knockdown, we investigated the consequences of expressing an HK2-targeted doxycycline (DOX)-inducible shRNA in our panel of HK1−HK2+ and HK1+HK2+ liver cancer cell lines." (PMID 29988332, 2018). "Our results showed that ectopic expression of miR-3662 decreased the levels of GLUT1, HK2, PKM2, and LDHA in liver cancer cells after treatment with the hypoxia mimetic CoCl2, while silencing miR-3662 increased their expression levels." (PMID 29748591, 2018). "Consistently, suppression of miR-3662 elevated the expression levels of GLUT1, HK2, PKM2, and LDHA in liver cancer cells." (PMID 29748591, 2018). "Herein, it was demonstrated that overexpression of lncRNA ZNF674-AS1 could remarkably inhibit the expression of PFKL, HK2, GLUT1, and PKM2 in the glycolysis metabolism of liver cancer cells." (PMID 35874626, 2022). "The results showed that TNFα was not expressed in the xenografts from two groups, and knockdown of HK2 did not regulate the expression of TNFα in liver cancer cells." (PMID 35603967, 2022).
liver cancer (continued). "Hexokinase 2 (HK2) could activate the transcription of ACSL4, leading to an increase in fatty acid β-oxidation activity which could promote liver cancer growth." (PMID 36497375, 2022). "Moreover, overexpression of lncRNA ZNF674-AS1 reduces the expression of HK2, PFKL, PKM2, and GLUT1 and inhibits glycolysis of liver cancer cells." (PMID 35874626, 2022). "Moreover, as expected from the TCGA data, these liver cancer cell lines fall into two subpopulations: HK1−HK2+ (Hep3B, HepG2, JHH5, JHH7, Huh7) and HK1+HK2+ (HLF, JHH6)." (PMID 29988332, 2018). "We find neither cell proliferation nor colony formation are affected by shHK2DOX HK2 inhibition for HK1+HK2+ HLF and JHH6 liver cancer cells, suggesting pharmacologic HK2 inhibition will not have therapeutic efficacy for HK1+HK2+ liver cancers." (PMID 29988332, 2018). "Liver cancers, however, no longer express HK4; instead, analysis of datasets of liver cancer samples revealed that, like many other cancers, HK2 is expressed in many liver tumors." (PMID 29988332, 2018). "We also find shHK2DOX HK2 inhibition plus OXPHOS inhibition (in our case with DPI) reduces, but does not completely suppress, xenograft tumor progression for Huh7 and Hep3B HK1−HK2+ liver cancer xenografts." (PMID 29988332, 2018). "While the majority of cancers including liver cancer, from many tissues of origin, express both HK1 and HK2, in many types of cancers, there exist subsets of HK1−HK2+ tumors, i.e., tumors that express only HK2." (PMID 29988332, 2018). "Depletion of HK2/ROCK2 by shRNA or inhibitors reduces TPC contractility to remodel vasculature, while combined treatment of HK2 inhibitor and doxorubicin enhanced the efficacy of chemotherapy drug against tumor growth in both lung and liver cancer animal models." (PMID 34650057, 2021). "Under hypoxic conditions, NONO binds to mRNAs of glycolytic genes GLUT1, HK2, and LDHA, promoting their splicing maturation and increasing glycolysis levels in liver cancer cells." (PMID 38785569, 2024). "Tested in combination with HK2 knockdown, neither NOX inhibitors (GKT137831, apocynin) nor NOS inhibitors (L-NAME or L-NNA) show synergy in HK1−HK2+ liver cancer cells." (PMID 29988332, 2018). "However, the synergism/synthetic lethality between HK2 knockdown and DPI is restricted to HK1−HK2+ cancer cells and is not observed in HK1+HK2+ liver cancer cells or in HK1+HK2+ cancer cells from other tissues." (PMID 29988332, 2018). "Therefore, if HK2 is required for HCC, targeting HK2 would selectively affect liver cancer cells without affecting normal hepatocytes." (PMID 29386513, 2018).
colon carcinoma (54 papers, 2012 to 2025). "Furthermore, molecular validation using Western blotting revealed elevated expression of colon cancer-associated markers, including HK2 and LDHA, in tumor-bearing liver tissues." (PMID 40647563, 2025). "The DANCR/miR-125b-5p/HK2 glycolysis axis has emerged as a promising therapeutic target to combat DDP resistance in colon cancer." (PMID 38877534, 2024). "Through positive regulation of a glycolysis-associated gene, HK2 (hexokinase 2), IGF2BP2 has been documented to control tumor metabolism in colon cancer." (PMID 38250159, 2024). "In contrast, DANCR knockdown in colon cancer cells can directly interact with and increase the expression of miR-125b-5p, which targets hexokinase 2 (HK2), thus suppressing glycolysis and enhancing DDP sensitivity in tumour cells." (PMID 38877534, 2024). "MiR-143-3p plays a role in the clinic mainly based on its molecular mechanism of targeting HK2 to regulate glycolytic energy metabolism in cells, which has been widely confirmed in colon cancer cells, oral squamous cell carcinoma cells, and other cells." (PMID 35534864, 2022). "LncRNA-DANCR-miR-125b-5p/HK2 is the key mechanism that mediates cisplatin resistance in colon cancer." (PMID 36189298, 2022). "We also found that C. tropicalis significantly enhanced the expression of enzymes associated with glycolysis, GLUT1, HK2, PKM2 and LDHA in colon tumor tissues, which was attenuated by TEPP-46 treatment." (PMID 36348389, 2022). "Resveratrol was also demonstrated to impair hexokinase-2 enzyme in human non-small cell lung cancer cells inhibiting Akt signaling pathway, and pyruvate dehydrogenase complex in colon cancer cells." (PMID 32013090, 2020). "We further identified glycolysis enzyme, hexokinase 2 (HK2), as a direct target of miR-125b-5p in colon cancer cells." (PMID 32766131, 2020). "The authors revealed that overexpression of miR-143 suppressed the HK2 expression, and subsequently lactate production was significantly reduced in colon cancer cells." (PMID 32878019, 2020). "In summary, our study reveals a new mechanism of the DANCR-promoted cisplatin resistance, presenting the lncRNA-DANCR–miR-125b-5p/HK2 axis as a potential target for treating chemoresistant colon cancer." (PMID 32766131, 2020). "Taken together, these rescue results verified the miR-125b-5p–suppressed glycolysis and CDDP resistance were through directly targeting HK2 in colon cancer cells." (PMID 32766131, 2020). "The negative correlation between miR-125b-5p and HK2 mRNA was further verified in colon tumors that higher HK2 mRNA expressions accompanied lower miR-125b-5p." (PMID 32766131, 2020). "Consistent results from the starBase of ENCORI indicated the mRNAs of HK2 in colon cancer tissues were negatively correlated with miR-125b-5p." (PMID 32766131, 2020). "Cell growth assay revealed that knockdown of HK2 attenuated the promoting effect of IL-22 on colon cancer cell proliferation." (PMID 28445985, 2017). "We demonstrated that IL-22 enhances aerobic glycolysis via targeting hexokinase 2 (HK2) in colon cancer cells." (PMID 28445985, 2017). "In vitro, interleukin-22 enhanced glucose consumption and lactate production via targeting hexokinase-2 in colon cancer cells." (PMID 28445985, 2017). "Elevated interleukin-22 mRNA expression was observed and positively correlated with hexokinase-2 in colon cancer tissues." (PMID 28445985, 2017). "Pro-inflammatory cytokine IL-22 was found to enhance aerobic glycolysis through a STAT3/c-Myc/HK2 signaling pathway in colon cancer cells." (PMID 28445985, 2017). "In this study, we observed that, in human colon cancer tissues, the aerobic glycolysis was enhanced along with elevated expression of glycolysis-related genes, including HK2." (PMID 28445985, 2017). "In summary, our data has revealed that pro-inflammatory cytokine IL-22 enhances aerobic glycolysis through a STAT3/c-Myc/HK2 signaling pathway in colon cancer cells." (PMID 28445985, 2017).
colon carcinoma (continued). "The bioenergetic measurements revealed that knockdown of HK2 reduced the glycolytic potential as well as mitochondrial respiration in colon cancer cells." (PMID 28179998, 2017). "Mechanistically, we found that PHLPP formed a complex with Akt and hexokinase 2 (HK2) in the mitochondrial fraction of colon cancer cells and knockdown of PHLPP enhanced Akt-mediated phosphorylation and mitochondrial localization of HK2." (PMID 28179998, 2017). "In summary, results from our study provide strong evidence suggesting that PHLPP has an important role in regulating glucose metabolism by controlling Akt and HK2 function in colon cancer cells." (PMID 28179998, 2017). "We further showed that inhibition of HK2 results in a reduction in cellular proliferation of DLD-1 colon cancer cells, an effect that resembles the effect of miR-143 overexpression." (PMID 22691140, 2012). "Here, we report that miR-143 targets and down-regulates the glycolytic enzyme hexokinase 2 (HK2) in colon cancer cell lines." (PMID 22691140, 2012). "Moreover, the AKT2 phosphorylation of hexokinase 2 has been demonstrated to enhance hexokinase activity and lactic acid production in colon cancer." (PMID 38396845, 2024). "Moreover, we also detected the expression of HK2 in colon tumor tissues in AOM/DSS and ApcMin/+ mice." (PMID 39141107, 2024). "Interestingly, miR-98 directly targeted hexokinase 2 (HK2) to suppress the Warburg effect and reduce glycolysis and proliferation in colon cancer cells." (PMID 38872210, 2024). "Similarly, CPNE1 belongs to the copines family that is highly conserved and soluble in eukaryotes, and can augment aerobic glycolysis and facilitate the advancement of colon cancer by modulating the AKT-GLUT1/HK2 pathway." (PMID 37532687, 2023). "In colon cancer cells, miR-143 was identified as targeting HK2 directly." (PMID 36013278, 2022). "Importantly, upregulation of SPI1 (p = 2.2 × 10−3), HK2 (p = 1.0 × 10−2) or PGK (p = 2.9 × 10−4) was found to be related with a poor survival in colon cancer patients." (PMID 34841706, 2021). "Downregulation of miR-143 in colon cancer cells could be responsible for promoting the metabolic reprogramming towards aerobic glycolysis with the upregulation of HK2." (PMID 32878019, 2020). "In this study, we identified HK2 as a direct target of miR-125b-5p in colon cancer." (PMID 32766131, 2020). "Importantly, silencing endogenous DANCR significantly induced the miR-125b-5p/HK2 axis, resulting in suppression of the glycolysis rate and increase in cisplatin sensitivity of colon cancer cell." (PMID 32766131, 2020). "We proposed DANCR specifically sponges miR-125b-5p to derepress the expression of HK2, a direct target of miR-125b-5p in colon cancer, presenting the DANCR/miR-125b-5p/HK2-glycolysis axis as a new therapeutic target for overcoming cisplatin resistance of colon cancer." (PMID 32766131, 2020). "MiR-143 has been shown to repress HK2 in colon cancer cells." (PMID 32843908, 2020). "PIM2 inhibitor also inhibited HK2 Thr473 phosphorylation in SW480 colon cancer cells." (PMID 29985480, 2018). "Since our results had clearly demonstrated that IL-22 enhanced aerobic glycolysis via targeting HK2 in colon cancer cells, we further explored whether HK2 accounts for IL22-mediated cancer cell proliferation." (PMID 28445985, 2017). "Further, HK2 may be a potential target for therapy in colon cancer with aberrant expression of IL-22." (PMID 28445985, 2017). "Also in the present study, our result showed that HK2 overexpressed in colon cancer tissues and knockdown of HK2 attenuated the stimulatory effect of IL-22 on glucose utilization and lactate production in DLD-1 cells." (PMID 28445985, 2017). "Futhermore, the miR-143-mediated HK2 regulation may also exist in breast and colon cancer, suggesting a common mechanism of miR-143 repressing HK2." (PMID 23251295, 2013).